LST1 (leukocyte specific transcript 1)
Description:
Possible role in modulating immune responses. Induces morphological changes including production of filopodia and microspikes when overexpressed in a variety of cell types and may be involved in dendritic cell maturation. Isoform 1 and isoform 2 have an inhibitory effect on lymphocyte proliferation.
Synonyms: B144; LST-1; D6S49E
Tractability: Antibody: its Gene Ontology location is reachable by antibodies, with high confidence; UniProt predicts a signal peptide or a membrane-spanning region; the Human Protein Atlas places it where antibodies can reach. PROTAC: its protein half-life has been measured.
Gene: Protein-coding gene on chromosome 6 (31,586,124 to 31,588,910, forward strand). Ensembl gene ENSG00000204482.
Subcellular location: Membrane; Golgi apparatus membrane; Endomembrane system
Subcellular location (Human Protein Atlas): Cytosol; Plasma membrane
Gene Ontology:
Biological process: dendrite development; negative regulation of lymphocyte proliferation; anatomical structure morphogenesis; immune response; cell morphogenesis
Cellular component: cytoplasm; membrane; plasma membrane; Golgi apparatus; endomembrane system; Golgi membrane
Genetic constraint (gnomAD): Loss-of-function variants: 8 observed, 7.03 expected, observed/expected ratio (o/e) 1.14, 90% interval 0.66 to 1.83. That is too few expected variants to judge how well the gene tolerates losing a copy. Missense variants: 113 observed, 107.07 expected, observed/expected ratio (o/e) 1.06, 90% interval 0.9 to 1.23. Synonymous variants: 49 observed, 44.59 expected, observed/expected ratio (o/e) 1.1, 90% interval 0.87 to 1.39.
Homologues: Orthologues: chimpanzee LST1 (99% identical), macaque LST1 (76% identical), rat Lst1 (51% identical), mouse Lst1 (48% identical).
Diseases named in the same sentence as LST1 in open-access papers:
LST1 is named in the same sentence as 31 diseases in open-access papers, as found by Europe PMC text mining. Sharing a sentence is not in itself a finding about the gene and the disease. The quoted sentences say what the papers report.
rheumatoid arthritis (3 papers, 2011 to 2021). A chronic, systemic autoimmune disorder characterized by inflammation in the synovial membranes and articular surfaces. "Some of these polymorphisms, thought to affect mainly LST1 gene expression and splicing, are associated with inflammatory conditions such as psoriasis, nephritis in systemic lupus erythromatosus and rheumatoid arthritis, or graft versus host disease severity." (PMID 33986741, 2021). "The expression of human LST1, specifically of splice variants encoding soluble isoforms, was increased in rheumatoid arthritis-affected blood and synovium and was up-regulated in response to IFN-γ." (PMID 21305040, 2011). "In humans, LST1 plays a role in the regulation of the immune response to inflammatory diseases such as rheumatoid arthritis, microbial infection or Rubella vaccine-induced immunity." (PMID 22905720, 2012). "Increased expression of LST1 in tissues affected by IBD or rheumatoid arthritis suggests that it may also be involved in other inflammatory conditions." (PMID 33986741, 2021). "Moreover, expression of LST1 is increased in rheumatoid arthritis patients and in colon samples from patients with inflammatory bowel disease (IBD)." (PMID 33986741, 2021). "During the past two decades multiple observations have been made of elevated LST1 mRNA and protein levels under inflammatory conditions and during disease, including IBD, rheumatoid arthritis, and influenza." (PMID 33986741, 2021).
bladder cancer (2 papers, 2020 to 2021). "In this paper, we demonstrate that TNTs formed by bladder cancer cells of mid and high-stages with invasive properties are functionally active and transport organelles, such as mitochondria, and proteins involved in bladder cancer malignancy and in nanotubes formation, such as RalA GTPase and LST1." (PMID 34944949, 2021). "TNTs observed in 5637 cells are functionally active and involved in mitochondrial trafficking; here, we demonstrated that TNTs in bladder cancer cells are also able to transport molecules important for TNTs development, such as LST1 and RalA, but not RalGPS2." (PMID 34944949, 2021).
COVID-19 (2 papers, 2022). A disease caused by infection with severe acute respiratory syndrome coronavirus 2. "Neutrophil transcripts which are robustly expressed in the uninfected state, including anti-proliferation and pro-apoptotic genes (LST1, G0S2, CPPED1, BTG2, PMAIP1) and anti-inflammatory genes (AMPD2, SEC14L1, ZFP36), are significantly downregulated in COVID-19 patients." (PMID 36466858, 2022).
Hypertension (2 papers, 2022 to 2025). The presence of chronic increased pressure in the systemic arterial system. "The results show that LST-1 and LST-2 increased the PPARγ protein levels significantly compared to control and L-NAME-induced hypertension in rats." (PMID 40137963, 2025). "Furthermore, we first investigated the expression patterns of the hypertension drug‐related genes in COVID‐19 patients by data set mining and modeling, suggesting the molecules being potentially involved in both hypertension and COVID‐19 pathology, such as JUN, LST1, and SLC18A2." (PMID 35656698, 2022).
influenza infection (2 papers, 2016 to 2021). "This was further corroborated by a subsequent study showing that LST1-deficient mice display higher susceptibility to influenza infection when compared to the wild type mice." (PMID 33986741, 2021). "Thus, Lst1 expression was found both during the innate and adaptive phase of the host response to influenza and peaked at the time point of T cell infiltration." (PMID 26817701, 2016). "However, deletion of Lst1 in DBA/2 J mice alone does not explain the high susceptibility of this strain to PR8M influenza infections." (PMID 26817701, 2016).
leukemia (2 papers, 2023). A malignant (clonal) hematologic disorder, involving hematopoietic stem cells and characterized by the presence of primitive or atypical myeloid or lymphoid cells in the bone marrow and the blood. "Differential gene expression analysis found that many upregulated genes in the C2 subtype were associated with increased leukemia cell survival, proliferation, and drug resistance, such as S100A8, S100A9, LILRB3, KLF4, LST1, and ITGB2." (PMID 37691822, 2023). "After constructing prognostic gene models in leukemia, we found that CD4, VDR and LST1 were the most significant prognostic risk genes." (PMID 37736548, 2023).
atherosclerosis (1 paper, 2022). A disease characterized by the build-up of fatty material and calcium deposition in the arterial wall resulting in partial or complete occlusion of the arterial lumen. "Overexpression of CXCL3, GK, FPR1, and LST1 was advanced recognition and intervention factors for unstable plaques, which might become targets for atherosclerosis rupture prevention." (PMID 36187340, 2022).
colitis (1 paper, 2021). Inflammation of the colon. "In addition, during DSS-induced colitis, LST1 deficiency had mitigating effects on gut inflammation further arguing against the possibility that the lack of LST1 in the gut promoted inflammation-driven changes in trabecular bone structure." (PMID 33986741, 2021). "In this work we describe basic features of LST1 deficient mice and analyze the role of LST1 in the dextran sodium sulphate (DSS)-induced colitis, a mouse model of IBD." (PMID 33986741, 2021). "Due to LST1 expression in the target tissues and our data showing effects of LST1 deficiency on several myeloid populations, we decided to induce DSS colitis in Lst1-/- male mice to test the effects of LST1 deficiency on the severity of this disease." (PMID 33986741, 2021). "The experiments with the mouse model of DSS induced colitis suggested altered response to intestinal microbiota in Lst1-/- mice." (PMID 33986741, 2021). "These connections to IBD and various other inflammatory conditions, prompted us to test the effects of LST1 deficiency on inflammatory response and, in particular, on DSS-induced colitis in mice." (PMID 33986741, 2021). "We show that the LST1 deficiency results in alterations in innate leukocyte subset composition and in milder progress of DSS-induced colitis, demonstrating LST1 involvement in the regulation of leukocyte homeostasis and inflammation." (PMID 33986741, 2021). "However, from the sixth day on, the colitis DAI of Lst1-/- mice appeared significantly lower than that of WT animals." (PMID 33986741, 2021). "Together, these data suggest that LST1 is not just an expression marker in colon samples of IBD patients but likely also an immune system regulator with moderate effects on leukocyte functions, homeostasis and development of colitis." (PMID 33986741, 2021).
Hyperglycemia (1 paper, 2025). An increased concentration of glucose in the blood. "This study initially identified LST1 as a pivotal regulatory factor in the co-occurrence of T2DM and ccRCC, emphasizing its essential involvement in the immune interaction within the hyperglycemia-induced microenvironment of ccRCC." (PMID 41488617, 2025).
inflammatory bowel disease (1 paper, 2021). A spectrum of small and large bowel inflammatory diseases of unknown etiology. "Previously published article showed elevated expression of LST1 in inflamed colon tissue from a patient with inflammatory bowel disease (IBD)." (PMID 33986741, 2021). "Moreover, LST1-deficient mice show significant level of resistance to dextran sodium sulphate (DSS) induced acute colitis, a model of inflammatory bowel disease." (PMID 33986741, 2021).
peritonitis (1 paper, 2021). Inflammation of the peritoneum (tissue that lines the abdominal wall and covers most of the organs in the abdomen). "Mmp9, Rgs2 and Zfp36l2 were downregulated in both IL-1β-induced conditions, while Lyz2 and Lst1 were downregulated in IL-1β-induced pneumonitis but not peritonitis." (PMID 34001893, 2021).
rubella (1 paper, 2010). A viral infection caused by the rubella virus. "We analyzed extended SNP-defined LTA, TNF, LST1, and HLA haplotype profiles and examined their contribution to humoral and cellular immune responses following the recommended two doses of the US licensed rubella-containing vaccine." (PMID 20668555, 2010).
Sepsis (1 paper, 2024). Sepsis is defined as life-threatening organ dysfunction caused by a dysregulated host response to infection. "We further characterized the cuproptosis-related gene LST1 to provide a theoretical framework for sepsis therapy." (PMID 38947313, 2024).
Ventricular hypertrophy (1 paper, 2025). Enlargement of the cardiac ventricular muscle tissue with increase in the width of the wall of the ventricle and loss of elasticity. "The current work demonstrated that decreased ventricular hypertrophy was linked to LST-1 and LST-2 restoring NO levels in L-NAME-induced hypertensive rats, in addition to enhancing the aortic and heart lesions’ histology score." (PMID 40137963, 2025).
virus infection (1 paper, 2017). "To determine whether wsp-1, the C. elegans orthologs of genes that interact with TNK2 (lst-1, dhs-7, and nck-1), or C. elegans genes that interact with WSP-1 (mig-13, mig-2, and nck-1) affect Orsay virus infection, we performed RNAi knockdown and evaluated Orsay virus replication." (PMID 28874467, 2017).
tumor (13 papers, 2017 to 2025). "Clinically, this implies that while LST1 reflects chronic inflammatory activation, it achieves greater diagnostic discrimination when combined with tumor-specific markers such as CA9, PBRM1, and HLA-exhaustion signatures." (PMID 41488617, 2025). "Alternatively, overexpression of either lst-1 or sygl-1 causes a germline tumor and so one might seek suppressors of those tumors or enhancers of the low penetrance pole-1 Glp phenotype." (PMID 35100350, 2022). "Consistent with a key role in self-renewal, both proteins are restricted to the GSC pool, and expanded expression of either LST-1 or SYGL-1 drives formation of a germline tumor." (PMID 37070766, 2023). "The reliance of SYGL-1 and LST-1 on FBF to promote tumor formation suggested two ideas for their molecular function." (PMID 29232700, 2017). "Intriguingly, modest SYGL-1 expansion increases size of the stem cell pool, and vast expansion of either SYGL-1 or LST-1 drives formation of a germline tumor." (PMID 29232700, 2017). "Third, spatial restriction of SYGL-1 and LST-1 prevents tumor formation, making them prototypes for a new class of oncogenes." (PMID 29232700, 2017). "Increasing the distribution of SYGL-1 expands the pool correspondingly, and vast overexpression of either SYGL-1 or LST-1 generates a germline tumor." (PMID 29232700, 2017). "The penetrance of tumor formation depended on both temperature and number of generations after removal from RNAi, but was close to 100% for both sygl-1(ubiq) and lst-1(ubiq) after two or three generations at 15°C." (PMID 29232700, 2017). "The augmented presence of immune ligand-receptor pairs such as IL-6, TNFSF13B, LGALS9-CD45, and HLA-E-KIR underscores the pivotal role of macrophages in modulating inflammatory responses, immune evasion, and reshaping the tumor microenvironment within the context of elevated LST1 expression." (PMID 41488617, 2025). "Notably, we found that macrophages were preferentially enriched in tumor tissues, while LST1+ non‐classical monocytes were predominantly present in the adjacent normal tissue." (PMID 41117057, 2025). "This hypothesis is strengthened by our experimental findings: LST1 knockdown reduced ccRCC cell migration and colony formation and inhibited tumor growth in vivo." (PMID 41488617, 2025). "Thus, SYGL-1 and LST-1 are each sufficient to drive “stemness” and their spatial restriction prevents tumor formation." (PMID 29232700, 2017). "Importantly, SYGL-1 and LST-1 can only drive tumor formation when FBF is present." (PMID 29232700, 2017). "First, SYGL-1 and LST-1 are not only required for GSC maintenance, albeit redundantly, but each on its own also drives stemness in the form of a tumor when ubiquitously expressed." (PMID 29232700, 2017). "We therefore hypothesized that LST1-mediated efferocytosis forms an immunological bridge, connecting the chronic inflammatory milieu of T2DM to the immunosuppressive tumor microenvironment of ccRCC." (PMID 41488617, 2025). "In current research, LST1, a gene encoding the MHC III region, has not been directly linked to tumour cells." (PMID 39400959, 2024). "In vivo, overexpression of LST-1 or SYGL-1 proteins in the presence of FBF-1 (a key partner of mRNA repression in stem cells) generates an overproliferation phenotype and leads to germline tumor formation." (PMID 35469833, 2022). "We have found that ubiquitous expression of either SYGL-1 or LST-1 protein drives formation of extensive germline tumors, and that their tumor-forming activities do not require GLP-1/Notch signaling from the niche." (PMID 29232700, 2017). "However, SYGL-1 and LST-1 no longer drive tumor formation in the absence of FBF." (PMID 29232700, 2017). "The first clue that LST-1 and SYGL-1 might function together with PUF proteins in a complex came from a genetic finding that forced overexpression of LST-1 or SYGL-1 does not lead to tumor formation in the absence of FBF-1 and FBF-2." (PMID 37070766, 2023).
cancer (5 papers, 2011 to 2025). A tumor composed of atypical neoplastic, often pleomorphic cells that invade other tissues. "Whether LST1 functions similarly in other chronic metabolic disorders or cancers also warrants further investigation." (PMID 41488617, 2025). "Finally, CDK2, LST1, NKD2 and RASL11B have also been implicated in a variety of cancer types." (PMID 22087225, 2011). "We explored them utilizing the pathway activity module of the GSCALite platform to determine whether these six genes (TYROBP, FCER1G, CD48, LST1, APOE, and APOC1) act through specific cancer pathways." (PMID 38515073, 2024).
infection (3 papers, 2016 to 2017). The state of being infected such as from the introduction of a foreign agent such as serum, vaccine, antigenic substance or organism. "Lst1 deficient mice exhibited significantly increased body weight loss at days 5 and 6 after infection and slightly increased lethality compared to infected wild-type mice." (PMID 26817701, 2016). "Only 3 genes each in the spleen (B2m, Lst1 and Edf1) and the brain (Six6, Cd163 and Bmp10) were modulated at all three time points after V3034 infection." (PMID 28446152, 2017). "Expression of Lst1 transcripts was up-regulated in C57BL/6 J mice after infection with influenza A virus (PR8M; H1N1)." (PMID 26817701, 2016). "There are four proinflammatory cytokines: tumor necrosis factor-alpha (TNFα), lymphotoxin alpha and beta (LTA and LTB), and leukocyte specific transcript-1 (LST1) in the class III region that are important in inflammation and infection." (PMID 27812316, 2016).
bacterial infection (2 papers, 2006 to 2016). "There are numerous reports describing that LST1 plays an important role in the immune response to inflammatory diseases in humans, in bacterial infections and in signal transduction." (PMID 26817701, 2016). "Furthermore, the expression of the Lst1 gene was shown to be up-regulated in response to lipopolysaccharide, interferon-γ and bacterial infections." (PMID 26817701, 2016). "The function of LST1 is still being elucidated but it has been shown to have an immunomodulatory function with a very strong inhibitory effect on lymphocyte proliferation and its expression is up-regulated in response to bacterial infection and inflammatory mediators." (PMID 17081307, 2006).
infectious disease (1 paper, 2010). A disorder directly resulting from the presence and activity of a microbial, viral, or parasitic agent in humans. "The leukocyte specific transcript-1 is a gene with extensive alternative splicing and is encoded within the TNF region of the HLA complex, and plays a role in inflammatory and infectious diseases." (PMID 20668555, 2010).
LST1 also shares sentences with these, for which no sentence is quoted: psoriasis (2 papers); Alzheimer disease (1); Arthritis (1); autoimmune disorder (1); clear cell renal cell carcinoma (1); depression (1); nephritis (1); ovarian carcinoma (1); pneumonitis (1); renal carcinoma (1); type 2 diabetes mellitus (1).